DDB2 (damage specific DNA binding protein 2)
Diseases named in the same sentence as DDB2 in open-access papers (continued):
Sharing a sentence is not in itself a finding about the gene and the disease.
tumor (continued). "Recent studies by others and us demonstrate that DDB2 is involved in transcriptional regulation of tumor promoting oncogenes, as well as, tumor suppressor genes." (PMID 30410671, 2018). "We further showed that treatment with a selective ALDH1A1 inhibitor blocked DDB2 silencing-induced expansion of CSCs, and halted orthotopic xenograft tumor growth." (PMID 29752431, 2018). "Taken together, results presented in this study show that this prime function of EMT regulation by DDB2 is conserved among different tumor types." (PMID 30410671, 2018). "Other than EMT-regulation, TGFβs have profound effects on tumor micro-environment, the role of TGFβ2 in DDB2-mediated EMT-regulation in HNSCC tumors needs further investigation." (PMID 30410671, 2018). "Chromosomal mutations in DDB2 cDNA in XPE patients are associated with repair deficiency and increased tumor susceptibility." (PMID 30410671, 2018). "This transcriptional regulatory function of DDB2 has been suggested to be partially responsible for its tumor suppressing potential." (PMID 26130719, 2015). "Enhanced expression of DDB2 in mice reduced UV induced skin carcinogenesis by both delaying the onset of tumor development and by attenuating the number of tumor occurrence in each mouse." (PMID 23109835, 2012). "Deletion of DDB2 in normal cells promotes spontaneous tumor growth in the absense of UV- or carcinogen-induced DNA lesions, probably due to an accumulation of unrepaired DNA lesions, leading to cell transformation." (PMID 18431487, 2008). "MBD2 was also shown to facilitate tumor metastasis by mitigating DDB2 expression." (PMID 41258082, 2025). "Interestingly, the damaged DNA binding 2 (DDB2), a well-known and potent inhibitor for tumor metastasis, was characterized in the cluster of genes whose expression was upregulated in the MBD2 siRNA transfected cells." (PMID 37142578, 2023). "Several studies have reported that the absence of DDB2 increases the risk of tumor formation in mice after UV induction." (PMID 36190612, 2022). "More importantly, we identified a novel AS factor DDB2, which may provide potential biomarkers for prognosis and tumor therapy in STAD." (PMID 36672781, 2022). "The high DDB2 expression level group had a low tumor purity degree (p = 0.0021)." (PMID 36672781, 2022). "To conclude, the present findings bring new tumor suppressor functions of DDB2 in PDAC cell models." (PMID 36568213, 2022). "Therefore, DDB2 plays a protective role as a tumor suppressor gene in the onset and development of OC." (PMID 36190612, 2022). "This study reveals an important tumor suppressor function of DDB2 in HNSCC." (PMID 30410671, 2018). "DDB2 has been considered a tumor suppressor and contributes to favorable treatment outcome." (PMID 28938550, 2017). "Since tumors are very heterogeneous; it is probable that in some tumors, high expression of AR may stimulate the expression of DNA repair-related genes including DDB2 and in these cases tumor cells may have developed other strategies to antagonize DDB2." (PMID 28212551, 2017). "Therefore, it is believed that DDB2 plays an important role in impeding tumor progression and tumor relapse." (PMID 26130719, 2015). "The tumor suppression function of DDB2 has been attributed to its in NER and apoptosis pathway." (PMID 23109835, 2012).
tumor (continued). "Therefore, the senescence induction by maintaining high ROS level is an important pathway through which DDB2 acts as a tumor suppressor." (PMID 23109835, 2012). "Taken together, these results provided evidence that DDB2 could play a role as a tumor suppressor in normal cells." (PMID 18431487, 2008). "DDB2 is known for its function in DNA binding while it also acts as a tumor suppressor." (PMID 21655371, 2008). "In addition, DDB2 expression was significantly (3.0-fold) higher in ER-positive than in ER-negative tumor samples (P = 0.0208) from 16 patients with breast carcinoma." (PMID 18431487, 2008). "Even if DDB2 is considered as a tumor suppressor, we proposed that this protein could play a role in breast cancer." (PMID 18431487, 2008). "Ddb2 or Xpc deficient mice do not have increased tumor susceptibility following DMBA exposure." (PMID 33937266, 2021). "However, since there is a diversity of signals capable of inducing EMT within the tumor microenvironment, detailed analysis is required to determine whether increased DDB2 expression can prevent progression of HNSCC." (PMID 30410671, 2018). "Also, one mechanism by which DDB2 plays a role in tumor cell proliferation could be related to its interaction with E2F1." (PMID 18431487, 2008). "Also, the down-regulation of the DDB2 gene observed in these cells may reflect tumor progression to a metastatic phenotype." (PMID 18431487, 2008). "To further validate the acquisition of malignant phenotype by DDB2 mutant cells, we assessed the level of HPRT, an enzyme regulating nucleotide synthesis whose overexpression and activity contribute to tumour progression." (PMID 38773406, 2024). "Recently, it has been reported that DDB2 is involved in epithelial-to-mesenchymal transition (EMT), key process in tumour invasiveness and metastasis formation." (PMID 38773406, 2024). "Mechanistically, MBD2 selectively bound to the methylated CpG DNA within the damage-specific DNA binding protein 2 (DDB2) promoter, by which it repressed DDB2 expression to enhance EMT process, thereby leading to tumor metastasis." (PMID 37142578, 2023). "Another study demonstrated that METTL14 facilitated global genome repair (GGR) by regulating m6A RNA methylation-mediated DNA damage-binding protein 2 (DDB2) translation and inhibits ultraviolet B- (UVB-) induced skin tumorigenesis." (PMID 37124930, 2023). "Collectively, our results demonstrate that systemic administration of pevonedistat significantly decreases DDB2 expression, which promotes enhanced sensitivity to cisplatin resulting in long-term survival of HNSCC tumor-bearing animals." (PMID 35428778, 2022). "DDB2 is a potent regulator of EMT and inhibits tumor migration and invasiveness of the studied PDAC cells." (PMID 36568213, 2022). "A significant difference in DDB2 protein expression was found between normal tissues and PDAC stages 2, 3 and 4 (p= 1.24e-8, p= 1.07e-3 and p= 5.51e-3 respectively) as well as tumor grades 1, 2 and 3 (p= 3.39e-2, p= 5.56e-11 and p= 6.27e-3 respectively)." (PMID 36568213, 2022). "Additionally, DDB2 maybe provide potential biomarkers for prognosis and tumor therapy in STAD." (PMID 36672781, 2022). "While mechanistic details remain, our data provide compelling evidence that USP44 stabilizes DDB2 and that this mechanism is crucial for efficient XPC recruitment and has physiological relevant roles in tumor prevention." (PMID 33937266, 2021). "Taken together, these results show that DDB2 represses TGFB2 mRNA expression irrespective of tumor types." (PMID 30410671, 2018). "Furthermore, in our models DDB2 is reduced or enhanced but the expression is not strictly knock down which is closer to the reality of tumor heterogeneity in PDAC patients." (PMID 36568213, 2022).
tumor (continued). "However, NEDD4L might exert a tumor-promoting effect, and the expression of NEDD4L was downregulated by DNA damage-binding protein 2 (DDB2)." (PMID 34869021, 2021). "However, DDB2 expression was not significantly elevated in overall BRCA tumor tissues compared to normal, suggesting that its contribution to chemoresistance may arise from chemotherapy-induced upregulation rather than constitutive overexpression." (PMID 41208896, 2025).
genetic disorder (1 paper, 2008). "In human, a point mutation in the DxR motif (R273H) of DDB2 leads to the XPE genetic disorder by abolishing its interaction with DDB1." (PMID 18551167, 2008). "In XP group E patients, a point mutation in the DxR motif (R273H) of the WD40 domain in DDB2 abolishes its interaction with DDB1 leading to the human genetic disorder XPE." (PMID 18551167, 2008).
metabolic disorders (1 paper, 2019). "Moreover, lack of DDB2 results in dysregulation of glucose uptake, implicating that DDB2 could play a critical role in the regulation of glucose metabolism and offer a potential target in therapy of metabolic disorders." (PMID 30923324, 2019).
neurodegenerative disease (1 paper, 2022). A disorder of the central nervous system characterized by gradual and progressive loss of neural tissue and neurologic function. "Single nucleotide polymorphisms (SNPs) of the DDB2 gene have been reported to be associated with aging-related degenerative diseases such as arteriosclerosis and neurodegenerative disease progressive supranuclear palsy." (PMID 36190612, 2022).
skin disorder (1 paper, 2022). Any deviation from the normal structure or function of the skin or subcutaneous tissue that is manifested by a characteristic set of symptoms and signs. "Mutations in DDB2 can cause xeroderma pigmentosum E (XP-E), a rare skin disorder characterized by extreme light sensitivity and increased risk of skin cancer." (PMID 35190564, 2022).
DDB2 also shares sentences with these, for which no sentence is quoted: endometrial cancer (3 papers); Cockayne Syndrome A (2); head and neck cancer (2); infection (2); lymph node metastasis (2); metastatic melanoma (2); xeroderma pigmentosum group C (2); African trypanosomiasis (1); atrophic gastritis (1); cholangiocarcinoma (1); Epstein-Barr virus infection (1); esophageal carcinoma (1); glioma (1); lung squamous cell carcinoma (1); neck cancers (1); nodular melanoma (1); osteoporosis (1); ovarian teratoma (1); ovarian tumor (1); rectal adenoma (1); renal carcinoma (1); retinopathy (1); sarcoma (1); small cell lung carcinoma (1); tuberculosis (1).